EIF5A2 (eukaryotic translation initiation factor 5A2)
Diseases named in the same sentence as EIF5A2 in open-access papers (continued):
Sharing a sentence is not in itself a finding about the gene and the disease.
colorectal cancer (22 papers, 2015 to 2025). A primary or metastatic malignant neoplasm that affects the colon or rectum. "In this study, we demonstrated that eIF5A2 was associated with the chemoresistance to doxorubicin in colorectal cancer cells." (PMID 26581310, 2015). "A recent study demonstrated that HERC3 could directly interact with EIF5A2 and promote the K27– and K48–linked ubiquitination degradation of EIF5A2 to regulate EMT in colorectal cancers." (PMID 35889210, 2022). "Moreover, previous reports have demonstrated that eIF5A2 is also associated with EMT progression in many cancers including colorectal carcinoma and HCC." (PMID 27028999, 2016). "For instance, miR-203 negatively modulates the level of eukaryotic translation initiation factor 5A2 (EIF5A2) in colorectal cancer, restraining cancer progression." (PMID 35055115, 2022). "Unlike most members of the EIF5A family that are universally expressed, EIF5A2 is tissue specific to the testis, brain, and tumor cells, especially in ovarian and colorectal cancer cell lines." (PMID 32605067, 2020). "In colorectal cancer, the overexpression of EIF5A2 has been reported to promote cancer aggressiveness by upregulating MTA1 to induce EMT." (PMID 32605067, 2020). "Another colorectal cancer study has demonstrated that EIF5A2 plays an important role in the chemoresistance to doxorubicin through EMT regulation." (PMID 32605067, 2020). "eIF5A2, in turn, was demonstrated to regulate MTA1 (metastasis-associated 1) via c-Myc in gastric cancer and colorectal carcinoma." (PMID 27433286, 2016). "In a recent study, eIF5A2 was found to be up-regulated in colorectal cancer patients, and it was suggested to be an independent predictor of shortened survival." (PMID 26581310, 2015). "EIF5A2 overexpression in colorectal carcinoma induces EMT by upregulating MAT-1 through c-Myc." (PMID 32605067, 2020). "In the present study, we aimed to investigate whether eIF5A2 was involved in the chemoresistance to doxorubicin in colorectal cancer." (PMID 26581310, 2015). "Hence, the present study aimed to investigate the biological role of eIF5A2 in colorectal cancer chemoresistance." (PMID 26581310, 2015). "Therefore, eIF5A2 inhibition may be a new potential strategy for the reversal of drug resistance in colorectal cancer therapy." (PMID 26581310, 2015). "Our finding is consistent with previous studies reporting that EIF5A2 promoted EMT and contributed to cell invasion, chemoresistance, and metastasis in several cancer types including HCC, colorectal cancer, bladder cancer, and OSCC." (PMID 33827661, 2021). "Silencing eIF5A2 enhanced the therapeutic efficacy of drugs in HCC, colorectal cancer, and breast cancer." (PMID 30175116, 2018). "Recently, it was found that eIF5A2 promotes doxorubicin resistance of colon cancer cells by regulating EMT, suggesting that inhibition of eIF5A2 can be used as a way to reverse the drug resistance of colorectal cancer." (PMID 35127825, 2021). "However, the relationship of eIF5A2 and drug resistance in colorectal cancer has never been explored." (PMID 26581310, 2015).
gastric cancer (17 papers, 2015 to 2025). A primary or metastatic malignant neoplasm involving the stomach. "In recent years, EIF5A2 has been shown to play a critical role in various cancers, including breast cancer, liver cancer, pancreatic cancer, and gastric cancer." (PMID 41358199, 2025). "Cisplatin resistance was negatively correlated with eukaryotic translation initiation factor 5A2 (EIF5A2) expression in gastric cancer cells." (PMID 34766149, 2021). "The induction of EMT in gastric cancer cells has also been proven to have a relationship with EIF5A2 overexpression while it decreases the cell sensitivity of cisplatin." (PMID 32605067, 2020). "Extensive studies have demonstrated that EIF5A2 participates in the proliferation, migration, invasion and chemotherapeutic resistance of hepatocellular carcinoma, esophageal cancer, gastric cancer, melanoma, etc.." (PMID 32466797, 2020). "Multivariate analyses identified EIF5A2 as an independent predictor for both overall survival (P=0.012) and disease-free survival (P=0.008) in gastric cancer patients." (PMID 25793713, 2015). "In addition, EIF5A2 regulates the resistance of gastric cancer cells to cisplatin by mediating epithelial–stromal transformation." (PMID 34796198, 2021). "Our findings indicate that EIF5A2 upregulation plays an important oncogenic role in gastric cancer." (PMID 25793713, 2015). "EIF5A2 may represent a new predictor for poor survival and is a potential therapeutic target for gastric cancer." (PMID 25793713, 2015). "In gastric cancer (GC), the overexpression of EIF5A2 was correlated with worse clinicopathological features moreover, patients with higher EIF5A2 expression ad shorter mean survival time." (PMID 32368188, 2020). "EIF5A2 upregulation has been reported in many human cancers, such as cervical cancer 36, HCC 37, bladder cancer 38, and gastric cancer." (PMID 32071552, 2020). "IHC results showed a positive correlation between EIF5A2 and MTA1 expression in gastric cancers (P<0.001)." (PMID 25793713, 2015). "EIF5A2 expression was measured in human gastric cancer cell lines, the immortalized gastric mucosal epithelial cell line (GES-1) and human gastric cancer tissues and knocked down by RNA interference or upregulated by EIF5A2 plasmid transfection." (PMID 25793713, 2015). "Eukaryotic translation initiation factor 5A2 (EIF5A2) (by up-regulating epithelial markers E-cadherin and β-cadherin, down-regulating mesenchymal markers Vimentin and N-cadherin mediate the EMT process to regulate the resistance of gastric cancer cells to cisplatin." (PMID 34422902, 2021). "EIF5A2 and its potential target metastasis-associated protein 1 (MTA1) expression were examined in 160 pairs of human gastric cancer and adjacent non-tumor specimens using immunohistochemistry (IHC) staining, and its correlation with clinicopathological features and survival was investigated." (PMID 25793713, 2015).
bladder cancer (13 papers, 2014 to 2025). "In bladder cancer cells, EIF5A2 promotes DOX resistance, EIF5A2 causes DOX resistance through activation of the TGF-β pathway." (PMID 40964657, 2025). "The knockdown of EIF5A2 can restrain the PI3K/Akt signaling pathway to prevent the growth of bladder cancer." (PMID 36290289, 2022). "In contrast, EIF5A2 was correlated positively with TGFβ signaling in bladder cancer by stabilizing STAT3 binding to the TGFR1 promoter." (PMID 33827661, 2021). "The knockdown of EIF5A2 in bladder cancer suggests that by increasing the enrichment of STAT3, EIF5A2 elevated TGF TGFβ1 expression by inducing EMT." (PMID 32605067, 2020). "We previously demonstrated that amplified in breast cancer 1 (AIB1) and eukaryotic initiation factor 2 (EIF5A2) overexpression was an independent predictor of poor clinical outcomes for patients with bladder cancer (BCa)." (PMID 27203388, 2016). "Recent other studies also showed that EIF5A2 play an important role in chemoresistance in breast cancer and promote bladder cancer cell aggressiveness." (PMID 25071013, 2014). "For example, GC7 combination therapy enhances the therapeutic efficacy of doxorubicin in bladder cancer and estrogen-negative breast cancer cells by inhibiting eIF5A2 activation and preventing the EMT." (PMID 27028999, 2016). "Additionally, some in vitro studies reported that knock-down or inhibition of EIF5A2 enhanced the chemosensitivity of HCC cells to 5-FU/doxorubicin and breast cancer cells and bladder cancer cells to doxorubicin." (PMID 26317793, 2015).
breast carcinoma (11 papers, 2014 to 2025). "TUG1 regulates the resistance of breast cancer cells to adriamycin by targeting binding to miR-9-5p and by acting on the downstream target eIF5A2." (PMID 38339157, 2024). "In fact, a higher expression level of EIF5A2 has been reported to be correlated with decreased doxorubicin sensitivity in breast cancer cell lines, and ablation of EIF5A2 enhanced chemosensitivity of HCC cells to 5-Fu." (PMID 27549330, 2016). "Similarly, in breast cancer cells, overexpression of EIF5A2 correlates with lower sensitivity to doxorubicin." (PMID 38770178, 2024). "Although eIF5A2 silencing increased eIF5A1 mRNA expression in breast cancer cells, including MCF7 cells, the inhibition of cell growth, in all three cell lines, induced by eIF5A2 silencing was stronger than that induced by eIF5A1 silencing." (PMID 40617352, 2025). "MiRNA-33a is another tumor-suppressor that impairs breast cancer metastasis and growth while promoting sensitivity to doxorubicin chemotherapy via inhibiting EMT, eukaryotic translation initiation factor 5A2 (eIF5A2)." (PMID 35236381, 2022). "The Kaplan–Meier curve suggested that the expression of eIF5A2, rather than eIF5A1, affects the survival of patients with breast cancer categorized by molecular subtypes." (PMID 40617352, 2025).
melanoma (11 papers, 2014 to 2024). A malignant, usually aggressive tumor composed of atypical, neoplastic melanocytes. "In melanoma, LINC00518 positively regulates EIF5A2 expression by directly binding miR-526–3p, suppressing melanoma (CMM) proliferation and metastasis." (PMID 39108268, 2024). "Take together, our research reveal the influence of LINC00520/miR-125b-5p/EIF5A2 on the biological progression of melanoma." (PMID 32466797, 2020). "miR-125b-5p overexpression melanoma cells showed the enrichment of the miR-125b-5p and EIF5A2 level that incorporated into RISC." (PMID 32466797, 2020). "The deep study of LINC00520/miR-125b-5p/EIF5A2 axis is helpful for us to identify new biomarkers or therapeutic target for melanoma patients." (PMID 32466797, 2020). "Increased expression of EIF5A2 has been suggested to enhance melanoma cell invasion with increasing MMP-2." (PMID 32605067, 2020). "In order to further verify the results of ceRNA analysis, the expression of miR-125b-5p and EIF5A2 were detected in 38 melanoma tissues and ANT." (PMID 32466797, 2020). "All results suggested that LINC00520 promotes EIF5A2 expression by decoying miR-125b-5p in melanoma." (PMID 32466797, 2020). "EIF5A2 was increased in melanoma tissues compared to ANT, and the same result were discovered by analyzing the TCGA-melanoma dataset." (PMID 32466797, 2020). "Here, we confirmed that miR-125b-5p exert its anti-proliferation and anti-metastasis effects by targeting EIF5A2 in melanoma." (PMID 32466797, 2020). "We also showed that LICN00520 promotes the growth and metastasis of melanoma in vivo through regulating miR-125b-5p/EIF5A2 axis." (PMID 32466797, 2020). "Take together, these results indicated that LINC00520 promotes the growth and metastasis of melanoma by decoying miR-125b-5p to promote EIF5A2 expression." (PMID 32466797, 2020). "Take together, these results demonstrated that LINC00520 promotes EIF5A2 expression by sponging miR-125b-5p in melanoma." (PMID 32466797, 2020). "We demonstrated that LINC00520 exerts its oncogene effect in melanoma by regulating Eukaryotic initiation factor 5A2 (EIF5A2)." (PMID 32466797, 2020). "LINC00520 facilitates the growth and metastasis of malignant melanoma by competitively binding to miR-125b-5p to liberate EIF5A2 mRNA transcripts, thereby promotes the EIF5A2 expression." (PMID 32466797, 2020). "In the network, the miR-125b-5p/EIF5A2 axis caught our attention because of miR-125b-5p was decreased and EIF5A2 was increased in melanoma tissue." (PMID 32466797, 2020). "These suggested that miR-125b-5p plays the role of tumor suppressor in melanoma by targeting EIF5A2." (PMID 32466797, 2020). "LINC00520 also promotes melanoma growth and metastasis in vivo by regulating miR-125b-5p/EIF5A2 axis." (PMID 32466797, 2020). "Consistent with the role of EIF5A2 in melanoma, functional studies as well as the clinical data indicate that EIF5A2 over-expression in HCC can promote tumor angiogenesis and tumor cell invasion." (PMID 25071013, 2014). "EIF5A2 has been shown to act as a new oncogene in many tumors, including melanoma." (PMID 32466797, 2020). "Also, LINC00520 (p-value = 0.00931) promotes the proliferation and metastasis of malignant melanoma by inducing the miR-125b-5p/EIF5A2 axis." (PMID 33392203, 2020). "LINC00520, miR-125b-5p and EIF5A2 were found to have a potential ceRNA correlation in melanoma." (PMID 32466797, 2020). "It was found that EIF5A2 also plays a role of oncogene in melanoma." (PMID 32466797, 2020). "We discussed whether LINC00520 exerts its oncogenic effect in melanoma by regulating EIF5A2 expression." (PMID 32466797, 2020). "EIF5A2 has also been proved to be the target gene of miR-125b-5p in melanoma." (PMID 32466797, 2020). "The mRNA and protein levels of EIF5A2 were repressed by LINC00520 siRNA in melanoma cells, and this inhibition effect could be reversed by miR-125b-5p inhibitor." (PMID 32466797, 2020).
melanoma (continued). "The same study also found the upregulation of vimentin, fibronectin, and α-SMA and downregulation of E-cadherin in EIF5A2-overexpressing melanoma cells, suggesting that EIF5A2 might induce EMT." (PMID 32605067, 2020). "We proved that miR-125b-5p exerts anti-cancer effects in melanoma by targeting EIF5A2." (PMID 32466797, 2020). "Previous study has demonstrated that both melanoma cell invasion and matrix metalloproteinase 2 (MMP-2) activity increased and decreased with EIF5A2 overexpression and knockdown, respectively." (PMID 32522053, 2020). "We also found that miR-125b-5p inhibitor abolish the role of LINC00520 siRNA on the EIF5A2 expression, proliferation and metastasis of BRAF-WT melanoma cells." (PMID 32466797, 2020). "LINC00520 siRNA, miR-125b-5p mimic, miR-125b-5p mimic together with EIF5A2 plasmid and LINC00520 siRNA together with miR-125b-5p inhibitor were transfected into melanoma cells." (PMID 32466797, 2020). "In our 38 melanoma tissue samples, LINC00520 and miR-125b-5p levels were inversely correlated, while LINC00520 and EIF5A2 levels were positively correlated." (PMID 32466797, 2020). "Our melanoma samples and public database further confirmed the network of LINC00520, miR-125b-5p and EIF5A2." (PMID 32466797, 2020). "EIF5A2, an AKT target gene which promotes melanoma cell invasion, has decreased expression following EphA6 knock-down." (PMID 26041887, 2015). "Moreover, we found that the inhibitory effect of LINC00520 siRNA on the EIF5A2 expression, proliferation, EMT, invasion and migration of melanoma cells were reversed by miR-125b-5p inhibitor." (PMID 32466797, 2020). "Also, eIF5A2 may induce EMT as demonstrated by increased mesenchymal markers and decreased epithelial marker in melanoma cell line with EIF5A2 overexpression." (PMID 32368188, 2020). "Moreover, it was reported that the regulation of the miR-125b-5p/EIF5A2 axis in melanoma, through the long intergenic non-protein coding RNA 520 (LICN00520), promotes the proliferation, invasion and migration of melanoma cells." (PMID 33050185, 2020).
prostate carcinoma (8 papers, 2020 to 2024). A carcinoma that arises from epithelial cells of the prostate gland. "Human prostate cancer samples in two independent cohorts showed a correlation between increased levels of EIF5A2 and upregulation of a PI3K pathway gene signature." (PMID 38654106, 2024). "Significant upregulation of EIF5A2 was verified in prostate cancer, and interference with EIF5A2 in PC-3 M IE8 cells decreased cell growth and lung metastasis in mouse models." (PMID 38584230, 2024). "EIF5A2 overexpression in prostate cancer cells therefore a potential prognostic predictive factor and therapeutic target." (PMID 34864817, 2021). "Expression of EIF5A2 also predicts poor prognosis of nasopharyngeal carcinoma patients, prostate cancer patients, and upper tract urothelial carcinoma patients, however the exact functions of eIF5A2 in these cancers should be further studied." (PMID 32368188, 2020). "The present study suggests that therapies targeting EIF5A2 in prostate cancer (PCa) may be effective in decreasing metastasis and inhibiting tumor grow." (PMID 32522053, 2020). "However, whether eIF5A2 could be as the target for prostate cancer (PCa) treatment is still unknown." (PMID 32522053, 2020). "Our study identified novel genes that promote prostate cancer formation through upregulation of the PI3K pathway, predicting a strategy to treat patients with genetic aberrations in these genes particularly relevant for EIF5A2 amplified tumours." (PMID 38654106, 2024). "Notably, androgen receptor (AR) signaling governs the expression of EIF5A2 in androgen-dependent cells, promoting prostate cancer metastasis by inducing EMT and elevating EIF5A2 expression." (PMID 38770178, 2024).
cervical cancer (7 papers, 2019 to 2025). A primary or metastatic malignant neoplasm involving the cervix. "The same study showed that EIF5A2 was up-regulated in aggressive cervical cancer, a protein that interacts with the HPV16 E6." (PMID 34885095, 2021). "Higher EIF5A2 expression was correlated with aggressive characteristics of cervical cancer, and serves as a biomarker for shorter overall survival and disease-free survival in FIGO stage II patients and in patients with a negative pelvic lymph node status." (PMID 32368188, 2020). "In cervical carcinoma, both EIF5A2 mRNA and protein levels are upregulated in cervical cancer tissues as compared with those in adjacent non-tumor tissues." (PMID 32368188, 2020). "In cervical cancer, overexpression of eIF5a2 as detected by immunohistochemistry correlates with poor patient prognosis." (PMID 31817792, 2019).
esophageal squamous cell carcinoma (6 papers, 2015 to 2024). Esophageal squamous cell carcinoma (ESCC) is a type of esophageal carcinoma (EC) that can affect any part of the esophagus, but is usually located in the upper or middle third. "An EIF5A2 increase has also been reported in esophageal squamous cell carcinoma and was shown to promote cell migratory and invasive abilities via the HIF1α-mediated signaling pathway." (PMID 27376958, 2016). "Interestingly, eIF5A2 positively regulates the expression of HIF-1α in esophageal squamous cell carcinoma cell lines." (PMID 35931669, 2022). "Interestingly, hypoxic stress induces the cytoplasm-to-nucleus translocation of eIF5A2 protein in esophageal squamous cell carcinoma (ESCC) cell lines, and eIF5A2 in the nucleus, promotes the transcription of HIF1α by binding to the promoter region of HIF1α." (PMID 32368188, 2020).
non-small cell lung carcinoma (6 papers, 2014 to 2024). A group of at least three distinct histological types of lung cancer, including non-small cell squamous cell carcinoma, adenocarcinoma, and large cell carcinoma. "Consistently, the knockdown of EIF5A2 inhibits the migration and invasion of non-small cell lung cancer cells." (PMID 33996900, 2021). "Additionally, overexpression of EIF5A2 is associated with poor prognosis in melanoma, nasopharyngeal carcinoma (NPC), cervical cancer, and non-small-cell lung cancer (NSCLC) patients." (PMID 38770178, 2024).